MPO (myeloperoxidase)
Diseases named in the same sentence as MPO in open-access papers (continued):
Sharing a sentence is not in itself a finding about the gene and the disease.
Granuloma (30 papers, 2012 to 2026). A compact, organized collection of mature mononuclear phagocytes, which may be but is not necessarily accompanied by accessory features such as necrosis. "Patients with anti-PR3 and anti-MPO often display differing disease phenotypes with anti-PR3 disease being particularly associated with granuloma formation." (PMID 33015103, 2020). "It has been previously reported that mice deficient in NADPH oxidase (chronic granulomas disease–like mice), which is an enzyme upstream of MPO, develop spontaneous granulomas in mucosal surfaces." (PMID 39133648, 2024). "In both the acute and chronic DSS models, the WT mice had significantly more granulomas per centimeter colon than the MPO-KO mice (P < 0.005)." (PMID 39133648, 2024). "Similar changes were reported for myeloperoxidase (MPO) in granulocytes, with particularly strong staining noted in stage IV granulomas between 8 and 27 wpc." (PMID 37901102, 2023). "More recently, our group have used a number of cell markers (CD3, CD4, Iba1, myeloperoxidase, Mac387) to describe presence and frequency of inflammatory and immune cells in granulomas up to 27 wpc." (PMID 37901102, 2023). "MPO was expressed in scattered granulocyte-like cells of stage I and II granulomas, as well as in the necrotic areas and inflammatory infiltrates of stage III and IV granulomas." (PMID 37808110, 2023). "Fucoidan from the brown algae Turbinaria ornata reduced the levels of inflammatory biochemical markers in cotton-pellet induced granulomas in rats, such as cathepsin D, myeloperoxidase (MPO) and C-reactive protein (CRP), somewhat comparable to dexamethasone." (PMID 38132941, 2023). "A large quantity of heterophils and activated macrophages is observed in late-stage granulomas, with high expression of MPO at the necrotic core and inner layers of the granulomas." (PMID 37808110, 2023). "P4 core biopsy, the only one available for RVC IHC staining, contained M-type RuV-associated granulomas and a small number of RVC+MPO+ neutrophils." (PMID 35003119, 2021). "The cores of these granulomas consisted of many tightly packed MPO+RVC+ neutrophils and were devoid of other cell types." (PMID 35003119, 2021). "Four weeks after infection, Socs3fl/fl lck cre mice displayed an increased severity of pulmonary pathology with granulomas containing large necrotic areas and elevated levels of neutrophil myeloperoxidase transcripts." (PMID 23853585, 2013). "Not surprisingly, we obtained contrasting data between WT and Jα18-/- mice, with higher proportion of MPO-positive cells within the granulomas of WT mice, whatever the size of granulomas (p<0.01)." (PMID 22457760, 2012). "The pathogenic hallmark of GPA is the loss of immune tolerance by T and B cells to neutrophil-derived proteins - primarily proteinase 3 (PR3) or myeloperoxidase (MPO) - leading to inflammation of vessel walls and the formation of peri- and extravascular granulomas." (PMID 40918843, 2025). "TB granulomas were more abundant in NE and MPO, and SARC granulomas in Z-form DNA." (PMID 39085192, 2024). "However, MPO was also highly expressed in stage IV granulomas at the late time points (8 and 24–27 wpi)." (PMID 37808110, 2023). "To translate our findings in an in vivo model, we tested the MPO inhibitor 4-aminobenzoic acid hydrazide (ABAH) in C3HeB/FeJ mice, which are highly susceptible to M. tuberculosis infection manifesting in neutrophil-associated necrotic granulomas." (PMID 35269694, 2022). "Further, because granulomatous inflammation is more prominent in PR3-ANCA+ GPA or PR3-AAV when compared to MPA or MPO-AAV, it can be hypothesized that PR3 is closely linked to the formation of granulomas." (PMID 34204207, 2021). "The induction of MPO mRNA was correlated with MPO-positive cell infiltration and with the number of granulomas (Spearman r = 0.68 and r = 0.65, respectively, p<0.0001), and inversely correlated with hepatic parasite burden (Spearman r = −0.49, p<0.001), this correlation being stronger in WT." (PMID 22457760, 2012).
Granuloma (continued). "Immunologic studies revealed positive p-ANCA and elevated MPO levels, the patient underwent pericardial window, and biopsy and pathology revealed granulation tissue in association with acute and chronic inflammation without granuloma." (PMID 40226538, 2025). "Four patients, earlier classified as GPA, all with granuloma on biopsy, were now assigned MPA due to MPO positivity." (PMID 38913291, 2024). "We detected strong signals for NE and MPO in biopsies of lymph nodes and lungs of patients with TB and SARC, respectively; the latter displayed the maximum MFI in the granulomas." (PMID 39085192, 2024). "Based on these findings we examined the colons of WT and MPO-KO mice from both acute and chronic DSS models for the presence of granulomas." (PMID 39133648, 2024). "RVC antigen was detected in CD206+ macrophages and multinucleated giant Langhans cells in the granuloma centers and infrequent RVC+MPO+ neutrophils were found in the surrounding areas." (PMID 35003119, 2021). "Conversely, MPA is characterized by systemic necrotizing vasculitis that pathologically demonstrates inflammation and necrosis of small-caliber blood vessels and occasionally medium-sized arteries without granulomas and with myeloperoxidase (MPO) positivity." (PMID 39949870, 2025). "Granuloma generates low score in the GPA towards GPA classification, but it is not included in the MPA at all, thus granuloma can now be a feature of MPA given MPO positivity or other items classifying towards MPA are present." (PMID 38913291, 2024). "We identified calprotectin+ myeloperoxidase+ CD11b+ neutrophils, CD14+/CD68+ monocytes/macrophages, CD3+ T cells, CD3-CD7+ NK cells, CD20+ B cells, CD3+ TCRγδ+ T cells, CD117+ ILC, cytokeratin+ epithelial cells and undefined cells with heterogeneous distribution across all 28 granulomas." (PMID 40749077, 2025). "Moreover, caseating granulomas were enriched in MPO, and non-caseating granulomas in Z-form DNA, respectively." (PMID 39085192, 2024). "However, granulomas are absent, and ANCA mostly interacts with the perinuclear antigen myeloperoxidase (MPO-ANCA)." (PMID 31286195, 2019).
multiple sclerosis (30 papers, 2006 to 2024). A progressive autoimmune disorder affecting the central nervous system resulting in demyelination. "Finally, MPO has been reported to protect against experimental autoimmune encephalomyelitis, an animal model for multiple sclerosis, with MPO‐knockout mice being more susceptible to these disease." (PMID 33959129, 2021). "Interestingly, upregulation of myeloperoxidase (MPO) expression is linked to pathological phagocytosis of myelin leading to demyelination in patients with multiple sclerosis." (PMID 31440125, 2019). "MPO is abundantly expressed in microglia in and around demyelinated lesions in Multiple Sclerosis in humans and rodents." (PMID 25576489, 2015). "In line, pharmacological inhibition of MPO reduced the severity of clinical symptoms in a murine model of Multiple Sclerosis." (PMID 25576489, 2015). "In experimental autoimmune encephalomyelitis (EAE) induced with synthetic proteolipid protein, a model of multiple sclerosis, MPO imaging has been tested for its ability to detect active plaques before clinical symptoms appearance in mice." (PMID 25505871, 2014). "In the same model of multiple sclerosis, another group used MPO imaging as an objective evidence of the therapeutic efficiency of an inhibitor (ABAH) of MPO." (PMID 25505871, 2014). "Indeed, increases in MPO levels, astrogliosis and microgliosis have been described in several neurodegenerative diseases, including AD, PD, and multiple sclerosis (MS)." (PMID 39500625, 2024). "Studies in animal models of Multiple Sclerosis (EAE), multiple system atrophy and in an animal model of amyotrophic lateral sclerosis indicate that blocking MPO activity lessens disease and improves motor behavior, pointing to the usefulness of developing MPO inhibitors." (PMID 36552550, 2022).
interstitial lung disease (29 papers, 2015 to 2026). A diverse group of lung diseases that affect the lung parenchyma. "Our study identified the neutrophil-associated biomarkers MPO, NE, and IL-6 as promising indicators with different suggestive roles in respiratory infections and interstitial lung diseases in patients with ASS and DM." (PMID 36199667, 2022). "Although MPO-ANCA positivity is often found in patients with interstitial lung disease (ILD) in clinical practice, a possible association between MPO-ANCA, MPA, and idiopathic interstitial pneumonias (IIPs) remains unclear." (PMID 34732182, 2021). "MPO-ANCA is commonly associated with MPA, characterized by renal involvement and pulmonary manifestations such as interstitial lung disease." (PMID 40100609, 2025). "These patients present morefrequently with anti-myeloperoxidase and anti-topoisomerase antibody profiles,with increased incidence of interstitial lung disease and renal involvement thanwould be expected in either disease independently." (PMID 36743820, 2023). "A 61-year-old Japanese woman was diagnosed with MPA based on interstitial lung disease and myeloperoxidase-ANCA positivity." (PMID 36343053, 2022). "We aimed to investigate the clinical, serological, and radiological features and prognosis of anti-MPO-positive interstitial lung disease (ILD) patients." (PMID 34207641, 2021). "Our case series describes the natural history of 17 patients with interstitial lung disease (ILD) and a positive myeloperoxidase‐antibody titre, over a mean follow‐up period of 4 years to help with a better understanding of the management of these patients." (PMID 40641494, 2025). "Our patient exhibited MPO-ANCA positivity (+6) and interstitial lung disease (+3), culminating in a total score of 9 points." (PMID 40988257, 2025). "CD8+CD28null Tang levels are further elevated in AAV patients with MPO+, p-ANCA+, interstitial lung disease, and active disease status." (PMID 39857611, 2024). "After the first description in 1990, the association between interstitial lung disease (ILD) and AAV was confirmed in 1994 in a Japanese study that reported a 43% prevalence of ILD in MPO-ANCA-positive patients with collagen vascular disease and or glomerulonephritis." (PMID 34207641, 2021). "In clinical settings, when a patient with PM has myeloperoxidase (MPO)-ANCA and interstitial lung disease (ILD), the patient can be classified as having overlap syndrome consisting of PM and MPA." (PMID 37959218, 2023). "Whereas both MPO- and PR3-ANCA+ patients can have lung involvement, those who are MPO-ANCA+ more often present with features of interstitial lung disease (e.g., fibrosing lung disease) rather than cavitary lesions and/or nodules characteristic of PR3-ANCA+ disease." (PMID 31867013, 2019). "Interestingly, 93.5% of these unclassifiable AAV patients were positive for MPO-ANCA, and 63.5% presented with interstitial lung disease (ILD), suggesting that this group may constitute a unique subset in the AAV spectrum." (PMID 27166610, 2016). "Interstitial lung disease (ILD), which usually emerges before a patient is classified as having AAV, is common in MPO-ANCA-positive AAV that manifests as various radiographic patterns, usually interstitial pneumonia, non-specific interstitial pneumonia, or bronchiolitis." (PMID 40095851, 2025). "Interstitial lung disease in AAV, especially anti-MPO ILD with or without systemic manifestations, is becoming more recognized, ANCA is not typically included in ILD workup and standardized criteria for diagnosis and classification of autoimmune-ILD are not available." (PMID 37089604, 2023).
lupus nephritis (29 papers, 2008 to 2025). Glomerulonephritis in the context of systemic lupus erythematosus. "In particular, patients with MPO-ANCA GN have enhanced loss of DNase I protein within the kidney compared with patients with lupus nephritis." (PMID 40632882, 2025). "MPO-DNA complex positivity was associated with the presence of lupus nephritis, antibodies to dsDNA, hypocomplementemia, and overall SLE activity, indicating the relationship between NETosis and the clinical and immunological manifestations of SLE." (PMID 37298160, 2023). "In conclusion, crescents are rare in MN, and usually indicate the presence of another underlying disease, for example lupus nephritis, or a separate disease, for example MPO-ANCA-GN and anti-GBM." (PMID 25187818, 2014). "These include scleroderma overlap syndromes with features of lupus nephritis, myeloperoxidase ANCA, proteinase 3 ANCA-associated GN or crescentic GN." (PMID 18474117, 2008). "For example, in a model of lupus nephritis, dependent on both autoreactive T cells and humoral immunity, we showed that MPO-deficient mice develop more severe renal injury in association with enhanced accumulation of cellular effectors, CD4 T cells, macrophages, and neutrophils." (PMID 26904693, 2016). "The concomitance between these autoimmune pathologies is unusual; there is a late-onset overlap syndrome between lupus nephritis accompanied by myeloperoxidase-antineutrophil cytoplasmic antibody and pauci-immune glomerulonephritis." (PMID 40212399, 2025). "In this case, the combination of immune complex-mediated lupus nephritis and pauci-immune necrotizing glomerulonephritis was confirmed by kidney biopsy and supported by MPO-ANCA positivity and hypocomplementemia." (PMID 41357727, 2025). "Elevated levels of the MPO-DNA complex can be regarded as a promising biomarker of lupus nephritis, disease activity, and immunological disorders in SLE patients." (PMID 37298160, 2023). "While IFNγ is protective in EAG, the Th1 pathway has also been shown to promote glomerular crescent formation and kidney injury in experimental lupus nephritis and MPO-AAV." (PMID 34721059, 2021). "Of the five individuals in whom anti-MPO antibody was strongly positive, all had renal involvement defined by an elevated creatinine with three having biopsy proven lupus nephritis." (PMID 31497427, 2019). "New studies also indicate that Annexin A1 in lupus nephritis is a component of NETs that seems of interest in view of the analogy with several other auto-immune conditions, such as small vessel vasculitis, in which components of NETs (i.e., MPO or proteinase 3) serve as antigens for antibodies." (PMID 29751523, 2018). "It was suggested that lupus nephritis might facilitate the process of MPO autoantibody formation by promoting neutrophil degranulation and priming neutrophils to increase surface expression of MPO." (PMID 24672300, 2014). "Elevated cfDNA, MPO-DNA complexes, citrullinated histone H3 (H3Cit), nucleosomes, and increased serum NE/MPO activity correlate with SLE activity and lupus nephritis." (PMID 41335221, 2025). "Patients with positive levels of the MPO-DNA complex were significantly more likely to have high SLE activity, positive antibodies to dsDNA, hypocomplementemia, and lupus glomerulonephritis." (PMID 37298160, 2023). "Experimental evidence for the pathogenesis of crescentic GN comes mainly from pre-clinical models, including lupus nephritis, experimental autoimmune GN (EAG; model of Goodpasture’s disease), MPO-ANCA vasculitis and nephrotoxic nephritis (NTN)." (PMID 34721059, 2021). "Of the five individuals in whom anti-myeloperoxidase (MPO) antibody was strongly positive, all had renal involvement defined by an elevated creatinine with three having biopsy-proven lupus nephritis." (PMID 31497427, 2019).
lupus nephritis (continued). "Patients with SLE and positive MPO-DNA complex levels were significantly more likely to have high SLE activity (χ2 = 5.25, p = 0.037), lupus glomerulonephritis (χ2 = 6.82, p = 0.009), positive antibodies to dsDNA (χ2 = 4.82, p = 0.036), and hypocomplementemia (χ2 = 6.72, p = 0.01)." (PMID 37298160, 2023). "Similarly, Tregs are protective in other models of crescentic GN including MPO-AAV and lupus nephritis." (PMID 34721059, 2021). "In addition, CD3-positive T cells, CD20-positive B cells, and MPO-positive neutrophils (data not shown) were assessed in the kidney biopsies of pediatric patients with lupus nephritis." (PMID 38331818, 2024).
acute myeloid leukemia (28 papers, 2008 to 2025). Acute myeloid leukemia (AML) is a group of neoplasms arising from precursor cells committed to the myeloid cell-line differentiation. "However, elevated levels of MPO have been associated with various inflammatory diseases, including infections, ischemia, atherosclerosis, and acute myeloid leukemia (AML)." (PMID 39857337, 2024). "MPO is a heme protein that serves as a major component of neutrophils, and high MPO expression was associated with favorable outcomes in patients with acute myeloid leukemia (AML)." (PMID 39202022, 2024). "Bone marrow morphology showed hypercellular marrow with 78.5% blasts, positive for myeloperoxidase staining, consistent with acute myeloid leukemia with maturation." (PMID 41561755, 2025). "Since MPO inhibitors are currently being developed as anti‐inflammatory agents this raises the possibility that repurposing of these potential new drugs could provide a means of suppressing secondary acute myeloid leukaemias associated with therapies containing TOP2 poisons." (PMID 38531625, 2024). "MPO is also highly expressed in certain cancers, such as colon adenocarcinoma, pancreatic adenocarcinoma, and acute myeloid leukemia, as inferred from the TIMER2 database." (PMID 35912260, 2022). "However, in acute myeloid leukemia (AML) caused by clonal expansion of early myelocytes insensitive to normal cellular signals, MPO expression is imbalanced." (PMID 33916434, 2021). "The CD13 and CD33 antigens and myeloperoxidase that characterize normal myeloid progenitors are abundantly expressed on almost all acute myeloid leukemia (AML) cells." (PMID 34203180, 2021). "An autopsy case (85-year-old Japanese male) of myeloperoxidase- (MPO-) positive acute myeloid leukemia with maturation (M1) accompanying megakaryocytic differentiation is presented." (PMID 33014496, 2020). "MPO is a lineage marker for acute myeloid leukemia and can serve as a prognostic factor." (PMID 29416750, 2018). "Acute myeloid leukemia cells (MPO + CD34-CD7-) were limited to intervillous maternal space." (PMID 28645262, 2017). "Myeloperoxidase test was positive in 2 (50%) patients of acute myeloid leukemia." (PMID 21593976, 2008). "For this, the edited T cells were co-incubated together with ML-2 acute myeloid leukemia (AML) cells that endogenously present the myeloperoxidase peptide, and which were transgenic for HLA-B7 or control HLA-B15." (PMID 30877233, 2019). "The presence of myelomonocytic specific markers, such as CD13, CD15, CD33, myeloperoxidase (MPO), CD14, and CD64 is useful for establishing the diagnosis of CD56‐positive acute myeloid leukemia, first presenting in the skin." (PMID 39210931, 2024). "MPO is regarded as an essential promotor in chemoresistant acute myeloid leukemia (AML) cells, preventing increased mitochondrial and cytosolic ROS levels and sensitizing AML cells to cytarabine treatment." (PMID 35386842, 2022). "Myeloperoxidase is a hallmark enzyme of acute myeloid lineage and the clinical relevance of the circulating MPO level in acute myeloid leukemia (AML) patients showed higher plasma MPO levels (range 1.0–9514 ng/mL) as compared to control subjects (range 3.5–20.6 ng/mL)." (PMID 29669993, 2018). "The most significant distinctive immunological markers between acute myeloid leukemia (M0) and acute lymphoid leukemia were found to be CD33 and myeloperoxidase." (PMID 21593976, 2008). "For instance, there is no requirement for MPO expression in myeloblasts of acute myeloid leukemia (AML)." (PMID 40075717, 2025). "Bone marrow evaluation confirmed the diagnosis of acute myeloid leukemia (AML), with myeloid blasts positive for CD33, CD34, CD13, and MPO on flow cytometry, and a significant monocytic component (M4 according to French-American-British (FAB) classification)." (PMID 39830569, 2024).